TG (thyroglobulin)
Diseases named in the same sentence as TG in open-access papers (continued):
Sharing a sentence is not in itself a finding about the gene and the disease.
autoimmune thyroid disease (continued). "Hashimoto’s thyroiditis (HT), an autoimmune thyroid disease (AITD), is characterized by infiltration of thyroid antigen-reactive T cells and by the presence of autoantibodies against thyroid antigens (thyroid peroxidase, TPO; thyroglobulin, Tg)." (PMID 31979029, 2020). "Other factors were also evaluated, including the development of eating habits and salt intake, prevalence of goiter, thyroid function and thyroid autoimmunity parameters (anti-TPO titers, anti-thyroglobulin antibodies (anti-Tg), and TSH receptor antibodies (TRAb)), and intelligence quotient (IQ)." (PMID 31061736, 2019). "Recognition of an autoantibody immunodominant region (IDR) on thyroglobulin and thyroid peroxidase (TPO) in spontaneous thyroid autoimmunity (humans and a mouse model) versus thyroid antibodies induced in rabbits or mice that are either restricted or not restricted to an IDR." (PMID 29326719, 2017). "Human autoimmune thyroid disease (AITD) is an organ-specific immune disease characterized by autoantibodies, such as anti-thyroglobulin (Tg) antibody, anti-thyroperoxidase (TPO) antibody and anti-TSH receptor (TSHR) antibody, mainly involving Hashimoto’s thyroiditis (HT) and Graves’ disease (GD)." (PMID 25429429, 2014). "Numerous authors are inclined to believe that coexistence of lymphocytic infiltrations, positive history of thyroid autoimmune diseases, or significantly high antibody levels (anti-TPO, anti-TG) prior to surgery had a significant impact on prognosis improvement." (PMID 23099542, 2013). "Indeed, traditional models of autoimmune thyroid disease, experimental autoimmune thyroiditis (EAT), are generated by immunizing mice with thyroglobulin protein in conjunction with an adjuvant, or by high repeated doses of Tg alone, without adjuvant." (PMID 21559421, 2011). "Epitope spreading has been demonstrated during experimental immunization with an immunogenic thyroglobulin peptide, but, to our knowledge, it has not been investigated in patients with auto-immune thyroiditis." (PMID 18853201, 2009). "In addition, the common autoimmune thyroiditis auto-antibodies, including anti-thyroglobulin (TG) and anti-thyroid peroxidase (TPO) antibodies, were not involved in the subsequent analysis due to their inaccessibility." (PMID 38708097, 2024). "Finally, because autoantibody (and possibly T cell) responses to TPO are similar to those to TSH receptor and thyroglobulin, manipulating T and B cell responses to TPO could pave the way for immunospecific treatment of autoimmune thyroid disease in general." (PMID 34667679, 2021). "Autoimmune thyroid disease (AITD) is one of the most common organ-specific autoimmune diseases, which is characterized by endocrine abnormalities and an elevated presence of thyroid antibodies, such as antibodies against thyroid peroxidase (TPOAbs) and antibodies against thyroglobulin (TgAbs)." (PMID 29312834, 2018). "They found that lymphocytes from the blood of either autoimmune thyroiditis patients or healthy people did not display a proliferative response upon stimulation of non-iodinated thyroglobulin, while iodinated thyroglobulin produced significant proliferation of lymphocytes from both groups." (PMID 25050783, 2014).
Hashimoto thyroiditis (174 papers, 2011 to 2026). An autoimmune disorder caused by the production of autoantibodies against thyroid tissue. "The most common cause of hypothyroidism is lymphocytic thyroiditis that is an autoimmune inflammatory disorder caused by the presence of thyroglobulin auto antibodies." (PMID 40346543, 2025). "Hashimoto’s thyroiditis, also known as chronic lymphocytic thyroiditis, is primarily associated with the presence of thyroid peroxidase antibodies and, to a lesser extent, thyroglobulin antibodies." (PMID 39776440, 2024). "Simultaneous detection of two antibodies that have been associated with thyroid ADs, and especially Hashimoto’s thyroiditis, i.e., anti-thyroglobulin (anti-TG) and anti–thyroid peroxidase (anti-TPO) model autoantibodies, was reported." (PMID 37571553, 2023). "In the multi-factor study, it was found that in the subgroup with age <45 years, tumor size, extrathyroidal extension, Hashimoto’s thyroiditis and serum thyroglobulin levels were independent risk factors for CLNM." (PMID 35250865, 2022). "WL-PTC was associated with a higher rate of anti-thyroglobulin antibodies (TgAb) (65% vs. 36%, p = 0.016) and lymphocytic thyroiditis (59% vs. 34%, p = 0.03)." (PMID 34033294, 2021). "Autoantigens associated with Hashimoto’s thyroiditis are derived from thyroglobulin and TPO, critical proteins within thyroxine (T4) synthesis." (PMID 32433950, 2020). "Variations in thyroglobulin are associated with susceptibility to autoimmune thyroid disease type 3, which include Graves’ disease and Hashimoto thyroiditis." (PMID 23915542, 2013). "Our predictions give strong support for thyroid-specific expression of the genes TPO (strong support) and TG (strong support) encoding proteins malfunctions of which cause Hashimoto's thyroiditis (OMIM ID 140300)." (PMID 23950964, 2013). "To date, the only thyroid-related genes associated with AITD are TG (the gene encoding thyroglobulin), in both Graves' disease and Hashimoto's thyroiditis, and TSHR (the gene encoding the thyrotropin receptor) restricted to Graves' disease." (PMID 22530160, 2012). "Although it is a rare complication of Hashimoto’s thyroiditis, the patient initially fulfilled the major diagnostic criteria: new-onset cognitive impairment, elevated serum anti-thyroid antibodies (anti-thyroglobulin), and exclusion of infectious, toxic, metabolic, or tumoral etiologies." (PMID 41446477, 2025). "While thyroid peroxidase (TPO) and thyroglobulin (Tg) antibodies are more strongly associated with Hashimoto’s thyroiditis, TRAb are typically present in Graves’ disease, though they may occasionally be detected in Hashimoto’s." (PMID 41217125, 2025). "A 2023 systemic review and meta-analysis on the possible benefits of Se on Hashimoto thyroiditis provided conservative evidence for supplementing patients with Hashimoto thyroiditis with Se over 6 months by demonstrating an associated decrease in thyroid peroxidase and thyroglobulin antibodies." (PMID 39408290, 2024). "The authors likely assumed that Hashimoto’s thyroiditis is hypothyroidism, although the same diagnostic criteria of Hashimoto’s thyroiditis are also applied in GD, namely hypoechogenicity of the thyroid parenchyma and abundance of antibodies to thyroid peroxidase (TPOAb) and thyroglobulin (TGAb)." (PMID 38737666, 2024). "Furthermore, there is expansion of immune response toward endogenous thyroid antigen, that is, the thyroid peroxidase and thyroglobulin which consequently cause extensive lymphocytic infiltration leading to Hashimoto's thyroiditis." (PMID 24198979, 2013). "The lack of data on the effect of L-thyroxine (LT-4) doses on the level of anti-TPO and anti-TG antibodies in Hashimoto's thyroiditis and the relationship with anthropometric measurements resulted in the desire to fill this niche." (PMID 41682650, 2026).
Hashimoto thyroiditis (continued). "The diagnosis of Hashimoto's thyroiditis relies on clinical presentation, thyroid function tests, detection of anti-thyroid peroxidase and anti-thyroglobulin antibodies, and ultrasound imaging." (PMID 41717291, 2026). "It is also known as lymphocytic thyroiditis, which is characterized by a diffuse lymphocytic infiltration and elevated levels of antibodies, such as those against thyroglobulin (anti-Tg) and thyroid peroxidase (anti-TPO)." (PMID 41226614, 2025). "Anti-thyroid peroxidase (anti-TPO) and anti-thyroglobulin (anti-Tg) antibodies are common in Hashimoto’s thyroiditis." (PMID 41157173, 2025). "The group that received the combination therapy had lower TSH levels, lower thyroglobulin antibody titers, and higher T3 and T4 levels in patients with Hashimoto’s disease." (PMID 41157173, 2025). "Thyroglobulin and thyroid peroxidase autoantibodies were positive, confirming autoimmune hypothyroidism." (PMID 39081695, 2024). "Our patient had elevated TSH with low normal T4, positive anti-TPO, positive anti-TG, and ultrasound neck revealing heterogenous, diffusely enlarged thyroid gland with linear echogenic septations, thereby meeting the criteria for Hashimoto’s thyroiditis." (PMID 39132944, 2024). "Anti-thyroperoxide antibodies (TPOAb), when paired with anti-thyroglobulin antibodies (Anti-Tg) are more indicative of Hashimoto’s disease." (PMID 38989384, 2024). "Hashimoto’s disease is a chronic lymphocytic thyroiditis characterized by the production of antibodies against thyroglobulin and thyroid peroxidase." (PMID 39771538, 2024). "Anti-thyroid peroxidase (TPO) and thyroglobulin antibodies were elevated, confirming a diagnosis of Hashimoto’s thyroiditis." (PMID 39483562, 2024). "Hashimoto’s thyroiditis (HT) is generally characterized by the presence of thyroid peroxidase and thyroglobulin antibodies, with a concomitant infiltration of lymphocytes in the thyroid." (PMID 38731922, 2024). "Firstly, the patient’s thyroglobulin antibodies and ultrasound findings were consistent with a diagnosis of Hashimoto’s thyroid." (PMID 39727679, 2024). "TPO antibody as well as thyroglobulin antibody were significantly elevated at 574 IU/mL and >2,500 IU/mL, respectively, values consistent with Hashimoto's thyroiditis." (PMID 39483562, 2024). "Antibodies against thyroid peroxidase (TPO) and thyroglobulin (TG) known as anti-microsomal antibodies have been detected in Hashimoto’s thyroiditis, Graves’ disease." (PMID 37907956, 2023). "Antibodies to thyroglobulin (IgG anti-TG) are also markers of Hashimoto’s disease, alongside IgG anti-TPO, although with a lower sensitivity and specificity." (PMID 37511088, 2023). "Anti-thyroglobulin and anti-thyroperoxidase antibodies were elevated consistent with Hashimoto’s thyroiditis." (PMID 37251685, 2023). "Thyroid peroxidase antibody (TPOAb) and thyroglobulin antibody were found to be positive in 90% of patients with Hashimoto's thyroiditis." (PMID 37190929, 2023). "For example, in an animal model of experimental autoimmune thyroiditis, the subcutaneous immunization of healthy animals with thyroglobulin using complete Freund’s adjuvant induces lymphocytic thyroiditis that simulates Hashimoto’s disease." (PMID 36838255, 2023). "Autoantibodies such as anti-thyroglobulin antibody (TgAb) and anti-thyroid peroxidase antibody (TPOAb) are involved in the pathogenesis of chronic thyroiditis." (PMID 37731007, 2023). "Hashimoto’s thyroiditis is distinguished by the presence of autoantibodies against thyroid peroxidase and thyroglobulin." (PMID 36980259, 2023). "Further workup revealed positive thyroperoxidase and thyroglobulin antibodies, thus confirming the diagnosis of Hashimoto’s thyroiditis." (PMID 37251685, 2023). "Negativation of autoantibodies against thyroglobulin and/or thyroid peroxidase was observed in four children with Hashimoto’s thyroiditis (one girl and three boys) of a total of eleven children diagnosed with Hashimoto’s." (PMID 37238410, 2023).
Hashimoto thyroiditis (continued). "Autoantibodies against thyroid peroxidase (TPO) and thyroglobulin (TG), which characterize Hashimoto’s thyroiditis (HT), and thyroid-stimulating receptors (TSHR), a marker for Graves’ disease (GD), were used in this study." (PMID 36002642, 2022). "Until now, several loci have been found to be associated with Hashimoto's thyroiditis, such as HLA-DR, immunoregulatory genes (CD40, FoxP3, CD25, CTLA-4, and PTPN22), and thyroid-specific genes (thyrotropin (TSH) receptors and thyroglobulin)." (PMID 34493981, 2021). "The BRAF V600E status, gender, family history, concomitant multinodular goiter, Hashimoto thyroiditis, multi-focality, multi-centricity, post-operative thyroglobulin level, and extent of neck dissection were tested." (PMID 34734568, 2021). "Of note, a pilot study showed that following a gluten-free diet for six months significantly reduced the serum titers of thyroid peroxidase antibodies and thyroglobulin antibodies in patients with Hashimoto’s thyroiditis." (PMID 34975767, 2021). "Thyroid peroxidase antibody (TPO-Ab) and thyroglobulin antibody (TG-Ab) are major indicators for the diagnosis of Hashimoto's thyroiditis (HT)." (PMID 33013669, 2020). "Degradation of thyroglobulin from the bloodstream by abzymes helps to minimize the autoimmune response and reduce harmful immunocomplex effects in Hashimoto’s thyroiditis." (PMID 32751323, 2020). "The present case with IMT exhibited Hashimoto thyroiditis with slightly elevated thyroglobulin and anti-thyroglobulin antibody levels." (PMID 32430041, 2020). "The proteolysis of thyroglobulin by abzymes can lead to dysfunction of the thyroid gland in Hashimoto’s thyroiditis." (PMID 32751323, 2020). "Hashimoto’s thyroiditis was confirmed according to serum levels of thyroglobulin and anti-thyroglobulin antibodies and morphology." (PMID 32430041, 2020). "Two patients (BSS5 and BSS7) who were diagnosed with Hashimoto’s thyroiditis were positive for anti- TG-Ab and one of them (BSS7) for TPO-Ab." (PMID 31924231, 2020). "Thyroid antibodies against thyroglobulin (TgAb) and thyroid peroxidase (TPOAb) are key markers of Hashimoto’s thyroiditis (HT), the most common autoimmune thyroid disorder." (PMID 30926877, 2019). "Anti-TPO antibodies are more common (90-95%) in Hashimoto's thyroiditis than anti-TG antibodies in Hashimoto's thyroiditis." (PMID 31428301, 2019). "An immunological link between CLT and DTC also lies in thyroglobulin and TgAb antibodies as it represents the primary target antigens for cellular cytotoxic and humoral immune reactions in both chronic lymphocytic thyroiditis and differentiated thyroid cancer." (PMID 29619749, 2019). "The cytotoxic T-lymphocyte antigen 4 (CTLA4) and thyroglobulin (TG) genes have been considered to be major genetic factors involved in the development of autoimmune hypothyroidism." (PMID 26963610, 2016). "Sera of Hashimoto's thyroiditis (HT) patients are known to exhibit elevated levels of anti-thyroglobulin IgG (TgAb IgG)." (PMID 25380293, 2015). "Increased levels of anti-TPO antibodies are usually found in about 95% and anti-TG antibodies in about 60% of the cases of autoimmune hypothyroidism, according to bibliography." (PMID 25003133, 2014). "The case reported here obviously is Hashimoto's thyroiditis which points to hypothyroidism and high microsomal and thyroglobulin antibody level denoting the autoimmune process of Hashimoto's thyroiditis." (PMID 24198979, 2013). "Thyroglobulin autoantibodies are found in less than 60% of patients with lymphocytic thyroiditis and 30% of Graves' disease patients." (PMID 23878745, 2013). "Together with thyroglobulin (TG) antibodies, these are the predominant antibodies in autoimmune hypothyroidism (AH)." (PMID 23878745, 2013). "This would be similar to the pathologic mechanism through which the autoantibodies to thyroglobulin, thyroid peroxidase and/or the thyroid-stimulating hormone receptor function in Hashimoto's thyroiditis." (PMID 21521495, 2011).
Hashimoto thyroiditis (continued). "The destruction of thyroid cells in Hashimoto’s thyroiditis (HT) is linked to several immune processes, both cellular and antibody-mediated, which involve thyroid autoantibodies against thyroid peroxidase (TPO) and thyroglobulin (Tg)." (PMID 40937419, 2025). "In this study, the level of thyroglobulin in serum was lower in Hashimoto’s thyroiditis, which may be due to the presence of thyroglobulin antibodies." (PMID 40496557, 2025). "Hashimoto’s thyroiditis is diagnosed based on of the clinical symptoms of thyroid hypofunction and biochemical evidence of the presence of antithyroid peroxidase antibodies and/or antithyroglobulin antibodies (anti-TG)." (PMID 38999993, 2024). "Another tobacco alkaloid, anatabine, also helped to reduce not only the incidence but also the severity of thyroiditis related to thyroglobulin, while a positive relationship between TC and chronic thyroiditis, such as Hashimoto’s thyroiditis, was found in some studies." (PMID 36875835, 2023). "Patients with Hashimoto’s thyroiditis usually have antibodies to thyroglobulin in their serum." (PMID 36810529, 2023). "The proinflammatory cytokine concentrations of IL-8, IL-10, IL-1B, and TNF-α were found to be significantly increased in patients with Hashimoto’s disease, who have anti-thyroid peroxidase antibodies and/or anti-thyroglobulin antibodies as compared to age- and sex-matched controls." (PMID 37241088, 2023). "Hashimoto's thyroiditis is characterized by the presence of thyroglobulin antibodies in the serum." (PMID 37190929, 2023). "In a mouse Hashimoto’s thyroiditis model induced by high-iodine water feeding and thyroglobulin immuno-injection, metformin reduced thyroglobulin antibody production and lymphocyte infiltration in thyroid associated with reduced number and function of Th17 cells and M1 macrophages polarization." (PMID 36614197, 2023). "It has been reported that vitamin D levels have inverse relationships with thyroglobulin antibodies, and therefore may be an indicator of Hashimoto’s thyroiditis." (PMID 35498400, 2022). "In the <45 years subgroup, factors that may have associations with CLNM (P<0.05), including gender, tumor size, degree of capsule invasion, Hashimoto’s thyroiditis and thyroglobulin, were included in the multivariate logistic regression model." (PMID 35250865, 2022). "Hashimoto thyroiditis (HT) is the most common autoimmune disease worldwide, characterized by chronic inflammation and circulating autoantibodies against thyroid peroxidase and thyroglobulin." (PMID 33746942, 2021). "The diagnosis of Hashimoto's thyroiditis is based on clinical features, typical ultrasound patterns, cytological examination of lymphocytic infiltration, and positive serum antibodies to thyroid antigens (including thyroid peroxidase and thyroglobulin)." (PMID 34493981, 2021). "Hashimoto’s thyroiditis (HT) is the most prevalent cause of chronic hypothyroidism in iodine sufficient regions, which stems from an autoimmune response against thyroid peroxidase (TPO) and/or thyroglobulin (Tg)." (PMID 33142736, 2020). "Thyrotropin receptor antibodies (TRAb) and/or thyroid stimulating antibody (TSAb) are usually used for diagnosis of Basedow’s disease, and thyroid peroxidase antibodies (TPOAb) and/or thyroglobulin antibodies (TgAb) are for diagnosis of Hashimoto’s thyroiditis." (PMID 32758269, 2020). "The patient had Hashimoto’s thyroiditis, and slightly elevated thyroglobulin and anti-thyroglobulin antibodies, suggesting that the immune disorder and infection could have contributed to IMT pathogenesis." (PMID 32430041, 2020). "Thus, a diagnosis of IMT was proposed on the basis of immunohistochemical findings and morphology, complicated by Hashimoto’s thyroiditis on the basis of the high serum levels of thyroglobulin and anti-thyroglobulin antibodies and morphology." (PMID 32430041, 2020).